CTNNB1 (catenin beta 1)
Diseases named in the same sentence as CTNNB1 in open-access papers (continued):
Sharing a sentence is not in itself a finding about the gene and the disease.
tumor (continued). "The tumor proteome of CTNNB1 mutated low-grade early-stage carcinomas differs from their WT counterparts." (PMID 41227323, 2025). "As the ß-catenin expression is the only recurrent molecular event due to CTNNB1 variants and is also detected in other mesenchymal neoplasms, we aimed to establish a molecular tumor profile of IPM." (PMID 40676219, 2025). "The high degree of colocalization of CTNNB1 and CCGs in the ST data from four tumor samples further implies a strong association between the two." (PMID 41312091, 2025). "In this study, unsupervised hierarchical cluster analysis (UHCA) revealed a significantly hypomethylated cluster enriched with CTNNB1-mutated ACPs, which was associated with increased tumor size." (PMID 40575267, 2025). "Concurrent with the germline and somatic mutations of DICER1, a pathogenic mutation in the CTNNB1 gene was also confirmed in our present tumor, which would explain the activation of the WNT/β-catenin in the morular structures." (PMID 40892116, 2025). "Based on the individual studies, the potential correlation between CTNNB1 mutation status and tumor behavior was not fully understood." (PMID 39620931, 2025). "A meta-analysis has demonstrated that CTNNB1 mutations significantly increase the odds of tumor recurrence and correlate with worse disease-free survival among patients lacking a specific molecular profile (NSMP)." (PMID 40004914, 2025). "For example, β-catenin (encoded by CTNNB1) is a component of the Wnt pathway, which plays an essential role in regulating tumor cell proliferation, angiogenesis, and metabolism." (PMID 40766332, 2025). "TERTp and CTNNB1 mutations have been reported to be significantly associated with older patient age, male sex, and smaller tumours (<5 cm)." (PMID 40650279, 2025). "Given the heterogeneous biological backgrounds of the differentially expressed proteins, we conducted a Gene Set Enrichment Analysis (GSEA) to further investigate the impact of CTNNB1 mutations on the tumor proteome." (PMID 41227323, 2025). "Nevertheless, response heterogeneity remains substantial and is partly explained by tumor-intrinsic programs such as WNT/β-catenin (CTNNB1) activation that associate with immune exclusion phenotypes and attenuated benefit from immune checkpoint blockade." (PMID 41181592, 2025). "IHC staining of matched pre-neoadjuvant tumor samples confirmed β-catenin that is encoded by CTNNB1 gene had higher expression in the IMPC group compared to that in the non-IMPC group." (PMID 40821778, 2025). "Initial tumor size, CTNNB1 mutation, and location should be factored into the initial decision-making process." (PMID 39620931, 2025). "This lower CD8 infiltration in CTNNB1 mutated samples was consistent across both intra-tumoral and stromal compartments (two-sided t-test p-value < 0.001 for intra-tumor CD8 TILs and 0.013 for stromal TILs)." (PMID 41227323, 2025). "Overall, β‐catenin expression was elevated in 93.75% of HCC tumor samples with CTNNB1 mutations, with an average increase of 11.21‐fold." (PMID 40344393, 2025). "WNTinib delays tumor progression and increases survival in CTNNB1-mutated HB models, providing rationale to explore its use in human HB." (PMID 41359441, 2025).
tumor (continued). "One-third of the patients in these studies needed active treatment (AT) after an initial AS approach, and tumor size, tumor location, and CTNNB1 mutation status were identified as potential predictors for the start of AT." (PMID 39620931, 2025). "In two tested samples, CTC-derived DNA revealed tumor-specific CTNNB1 mutations (codons 32–37 and 41–45), while the matched plasma cfDNA from the same patients tested negative for CTNNB1 mutations." (PMID 41203725, 2025). "This tumour phenotype is characteristic of PB-type promoted liver tumours and is a consequence of b-catenin activation resulting from mutations in exon 3 of the Ctnnb1 gene." (PMID 40044833, 2025). "The CTNNB1 gene, which encodes β-catenin, often shows abnormal activation in PC cells, closely linked to tumor proliferation, survival, and metastasis." (PMID 40593037, 2025). "To explore the efficacy of ceritinib in a preclinical in vivo setting, we used an established patient-derived xenograft model, in which the highly proliferative and CTNNB1-mutated HB tumor PDX282 was subcutaneous propagated in immunocompromised mice." (PMID 40968384, 2025). "Among the key EMT-associated nodes identified, CTNNB1 (β-catenin) plays a central role in canonical Wnt signaling and is known to drive stemness, therapeutic resistance, and tumor aggressiveness in NSCLC." (PMID 40787462, 2025). "The impact or significance of the presence of CTNNB1 mutation in this extremely rare tumor subtype has yet to be determined." (PMID 39436475, 2024). "Mutations occurring in exon 3 of the CTNNB1 gene induce an upsurge in β‐catenin levels, consequently contributing to the formation of neoplasms characterized by hair matrix differentiation." (PMID 39139622, 2024). "TTK inhibitors exhibit heightened sensitivity toward tumor cells harboring CTNNB1 mutations, implicating CTNNB1 mutations as predictive genetic markers for patient response to TTK inhibitor therapy." (PMID 39100078, 2024). "Higher incidence of vascular invasion and greater tumour size have been also observed in the CTNNB1 mutated group of HCC cases." (PMID 39261716, 2024). "In our cohort, 34.48% (22/64) of patients exhibited positive PD-L1 expression in tumor cells, and this expression was associated with GAs in CTNNB1 and BLM." (PMID 38439030, 2024). "Considering the direct association between β-catenin aberrancy and CTNNB1 mutations—a well-known tumor driver—it is reasonable to assume the presence of mutant CTNNB1 in these glands." (PMID 38539494, 2024). "To identify the potential kinase that associated with SHC1, the phosphorylation of CTNNB1 at Ser552, and the tumor metastasis, we referred to the public database and performed further correlation analysis." (PMID 38360860, 2024). "The less-aggressive classes were preferentially found in S-I and S-II tumours, consistent with the CTNNB1 mutations." (PMID 39261716, 2024). "Molecularly, all tumor models exhibit common driver mutations in CTNNB1 and AXIN1, with TLCT models showing the characteristic TERT mutation, and some models progression-associated alterations in the NFE2L2 and NRAS genes." (PMID 39529166, 2024). "CTNNB1 mutation leads to the activation of the Wnt pathway, and prevents the establishment of an inflammatory tumor microenvironment by T cells in various types of cancer." (PMID 39509381, 2024). "Looking into the AC4 cluster, its distribution was similar among all tumour samples except for one CPA with CTNNB1 mutation (CPA‐3), where it represented ∼36% of the cells." (PMID 39167619, 2024). "As tumorigenesis of ACP is associated with activation of the WNT/β-catenin pathway by CTNNB1 mutations, we examined the Wnt signaling activity throughout the tumor tissue and found moderately increased activity in tumor cells." (PMID 39483146, 2024).
tumor (continued). "Key genes implicated include WT1, which is associated with syndromic presentations such as WAGR syndrome and CTNNB1, with non-syndromic cases displaying a spectrum of mutations impacting tumor behavior and response to therapy." (PMID 39062028, 2024). "CTNNB1-mutated tumours are grouped into the S3 class that retains more hepatocyte like-phenotype with well-differentiated tumours." (PMID 39261716, 2024). "CTNNB1 accumulates in the nuclei of tumor cells when the Wnt signaling pathway is activated, resulting in the loss of epithelial integrity and increased tumor invasion and metastasis." (PMID 38191906, 2024). "Elsewhere, it has been shown that SMAD has a prognostic value in GC patients; meanwhile, CTNNB1 mutations have decreased expression of βcatenin, which is associated with poor tumor differentiation and shorter overall survival." (PMID 38392199, 2024). "To confirm the tumor origin of the organoids, we performed targeted sequencing on CTNNB1 exon 3 and verified the presence of point mutations or deletions, as identified in the original tumors, in all organoids." (PMID 39567475, 2024). "Second, our results also demonstrate that CTC analysis brings complementary information to ctDNA in almost 70% of the cases with some CTC ‘private’ mutations in genes implicated in immune evasion or tumor dissemination mechanisms like CTNNB1 and CDKN2A." (PMID 38898234, 2024). "We show significant tumor responses in multiple β-catenin-mutated immunocompetent HCC models to a novel siRNA encapsulated in lipid nanoparticle targeting CTNNB1 (LNP-CTNNB1)." (PMID 39711542, 2024). "Tumor cells, which were unambiguously identified through the cellular mutation status of the driver CTNNB1 mutations, were clustered into 6 subsets." (PMID 39223689, 2024). "Genetic analysis revealing a CTNNB1 mutation underscored the importance of molecular profiling in understanding tumor behavior and guiding postoperative monitoring." (PMID 39092348, 2024). "Exome sequencing of primary HB not only demonstrated an unexpectedly low mutation rate, with an average of only 2.9 mutations per tumor, but also confirmed that CTNNB1 mutations and deletions were present in 78 out of 88 (89%) of the tumors examined." (PMID 38390281, 2024). "In contrast, CTNNB1 mutations were identified together with the 11p15.5 alterations in their corresponding tumor counterparts in 12 out of 13 patients." (PMID 37932266, 2023). "Such mutations of exon 3 in CTNNB1 gene occur in up to 20% of tumours, more often in low grade, early ECs." (PMID 36969079, 2023). "Based on the resected HCC of patients, their report showed that CTNNB1 mutations were associated with tumor differentiation, HBV infection, and clinical prognosis." (PMID 37733676, 2023). "Following RNA and DNA isolation from formalin-fixed, paraffin-embedded (FFPE) tumor tissues, the molecular classification and CTNNB1 mutation analysis were performed by nCounter and Sanger sequencing, respectively." (PMID 37746264, 2023). "Multivariable analysis using tumor size and CTNNB1 mutation status only identified the presence of a S45F mutation (HR = 4.64 [95% CI 1.38–15.8]) as a predictive factor for the initiation of active treatment." (PMID 35166264, 2023). "Nevertheless, a further study of CTNNB1-mutated NSCLCs reported a heterogeneity of aberrant β-catenin staining within the same tumor, which casts doubt on the efficacy of β-catenin IHC as a predictor of a CTNNB1 mutation in NSCLC." (PMID 37347751, 2023). "In this study, significant heterogeneity was found when discussing the relationship between CTNNB1 mutations and 5-year overall survival and tumor size in the selected studies." (PMID 37733676, 2023). "The APC gene is a well‐known tumour suppressor gene, associated with CTNNB1, with diverse functions, that is cell migration and adhesion." (PMID 36625073, 2023).
tumor (continued). "Comprehensive analysis of clinical samples has identified immunological and molecular classification of HCC, and the CTNNB1-mutated subtype exhibits distinctive characteristics of immunosuppressive tumor microenvironment." (PMID 37733676, 2023). "Timbergen et al28 also suggested an association between CTNNB1 mutation and tumor size based on the results of their meta-analysis." (PMID 35166264, 2023). "In cases of metastatic recurrence, CTNNB1 variants were identified in 20–33% (1/5 to 1/3, as only 3 of the 5 cases had a Sanger-sequencing-confirmed tumor CTNNB1-mutation) of samples, with a VAF of 1.1%." (PMID 38201440, 2023). "Out of 14 tumor samples from the 9 patients with germline WT1 variants, 10 (71.4%) were found to have acquired tumor somatic activating variants in exon 3 of CTNNB1, which codes for the Wnt pathway effector transcription factor β-Catenin." (PMID 38110397, 2023). "We further investigated the association between VEGFA/CTNNB1/MMP7/CD44 oncogenic expressions with selected immune cells in the tumor microenvironment (TME)." (PMID 36672201, 2023). "In all these patients, HB tumors derived from the malignant transformation of the mosaic clones with 11p15.5 alteration with additional CTNNB1 oncogenic mutation in the tumor cells." (PMID 37932266, 2023). "CTNNB1 variants were the most common tumor somatic genetic variants in this cohort and converged on Serine at codon 45, a critical residue that is phosphorylated to control nuclear translocation of β-Catenin22." (PMID 38110397, 2023). "Several potential clinicopathological factors associated with change in treatment strategy and risk of progression or recurrence have been evaluated in retrospective studies, such as tumor size, tumor location, and CTNNB1 mutation status." (PMID 35166264, 2023). "WT1 and CTNNB1 variants often co-occur in WT and the spatial distribution of CTNNB1 variants has been demonstrated to exhibit intra-tumor genetic heterogeneity." (PMID 38110397, 2023). "Previous studies have demonstrated that mutation of CTNNB1 or TTN of tumor cells can affect the activation and recruitment of immune cells, thus regulating the infiltration of immune cells." (PMID 37593098, 2023). "The WNT/CTNNB1 signaling pathway was recently reported to suppress immune cell infiltration, and this signaling activation in the tumor site was negatively associated with ICI treatment in HCC." (PMID 35205631, 2022). "β-Catenin (encoded by CTNNB1) is upregulated in the tumor tissues of patients with PC and induces carcinogenesis, invasiveness, metastasis, angiogenesis, and therapeutic sensitivity of PC cells and tumors." (PMID 35591866, 2022). "Of all the subtypes, notably, CTNNB1-mutated HCC with activating WNT/β-catenin pathway has a well-differentiated tumor phenotype and lacks immune cell infiltration." (PMID 36483039, 2022). "All PDS had high expression of HB genes and retained their parent tumor mutations in CTNNB1, indicating that they grew from tumor cells." (PMID 36008377, 2022). "Recent advancements in targeted reprogramming [like selective ablation of Wt1 in Ctnnb1 (cadherin-associated protein β1) over-expressing Sc results into Lc cell-like tumor development, manipulation of SF1, GATA4,etc." (PMID 36686449, 2022).
tumor (continued). "The CTNNB1 mutations detected in human neoplasms are frequently missense mutations, and nearly all of them have been localized in exon 3, the phosphorylation sites for GSK-3β." (PMID 36428715, 2022). "In support, castration resistance has also been observed in Nkx3.1-CreERT2 Ctnnb1+/Δex3 mice, although others have reported early castration in this model causes tumor regression." (PMID 35204808, 2022). "Subsequently, we observed that patients with tumours harbouring the CTNNB1 mutation showed a poor prognosis, with a similar RFS to the high-risk group (late curves overlapping)." (PMID 35205661, 2022). "We performed deep sequencing with a mean depth of 31,310X (±8,924) to characterize the Kras and Ctnnb1 hotspot alleles in the tumor samples." (PMID 36313038, 2022). "Tumours with mutations in CTNNB1 tend to have low-grade histology, low rates of myometrial invasion with low rates of LVSI." (PMID 35531470, 2022). "The metastasis was enriched for tumor regions with increased CTNNB1 (encoding beta-catenin), which were negatively associated with the expression of T-cell surface proteins and antigen presentation machinery." (PMID 35264439, 2022). "FGFR2 mutations were also significantly more common in MSI-positive tumours than CTNNB1 mutations and appeared to have shorter disease-free survival." (PMID 35269800, 2022). "The samples with CTNNB1 mutations showed up-regulated CTNNB1-HCC class pathway compared with CTNNB1 wild-type tumor samples, suggesting that the discovered CTNNB1 mutations in this cohort induced the activation of WNT/β-catenin pathway." (PMID 34986867, 2022). "For HCC, as with other malignancies, gain-of-function mutations in the CTNNB1 (β-catenin) gene have recently been shown to strongly impact the tumor immune microenvironment." (PMID 36002545, 2022). "Tumor-associated mutations in CTNNB1 exon three target the N-terminal phosphorylation domain of β-catenin protein, resulting in impaired phosphorylation by GSK-3β, increased β-catenin protein stabilization, and nuclear β-catenin protein accumulation." (PMID 35053583, 2022). "In the mouse model, all of the tumours carry somatic deletions of the third exon of the CTNNB1 gene that encodes β-catenin." (PMID 34916592, 2022). "The CTNNB1 mutation leads to the overactivation of beta catenin, which results in the aberrant signalling of the Wnt pathway, contributing to tumour progression." (PMID 35205661, 2022). "The antitumor efficacy of BC2059 was evaluated in a panel of desmoid tumor cell lines representing the different CTNNB1 mutations found in desmoid patients." (PMID 36240209, 2022). "Of note, biallelic ARID1A mutated tumours had the highest immune infiltration and PD-L1 scores, contrary to tumours with CTNNB1 mutation." (PMID 36613564, 2022). "In this study, spatial profiling revealed T-cell exclusion by the tumor, which was associated with increased expression of CTNNB1 in a metastatic lesion following disease progression." (PMID 35264439, 2022). "The presence of CTNNB1 mutations is associated with an increased tumor size, microvascular invasion in HCC." (PMID 35454818, 2022). "This is first implicated by transcriptomic upregulation of Wnt signalling pathway in S2 tumours or activation of the CTNNB1 pathway that has been linked with immune exclusion in previous studies." (PMID 35301339, 2022). "In contrast to activating CTNNB1 mutations, which almost always occur as somatic events in the tumor, pathogenic APC mutations frequently are germline events." (PMID 36181537, 2022). "We sequenced cDNA and genomic DNA from tumours, identifying in every case a mutation leading to deletion of CTNNB1 exon 3; in one case the deletion encompassed part of exon 4 also." (PMID 34916592, 2022).